MIR1262 (microRNA 1262)
Synonyms: hsa-mir-1262; MIRN1262; mir-1262
Gene: MicroRNA gene on chromosome 1 (68,183,518 to 68,183,610, reverse strand). Ensembl gene ENSG00000221203.
Homologues: Orthologues: chimpanzee ptr-mir-1262 (100% identical).